YY1 (YY1 transcription factor)
Diseases named in the same sentence as YY1 in open-access papers (continued):
Sharing a sentence is not in itself a finding about the gene and the disease.
tumor (continued). "Yin-yang-1 (YY1) is a DNA-binding protein with a zinc finger structure and is an important transcription factor that regulates the proliferation, migration, and EMT of tumor cells." (PMID 40607251, 2025). "Moreover, 3-HAA inhibits tumor growth and reduces tumor weight in vivo, triggering apoptosis in HCC cells by interacting with YY1." (PMID 38462620, 2024). "Thus, targeting YY1 inhibition in CD8 T cells and tumor cells is a novel strategy to evade immune evasion and enhance the anti-tumor immune response, as well as to inhibit various pro-tumorigenic activities." (PMID 39796650, 2024). "YY1 interacts physically with the suppressor of zeste 12 (SUZ12) and recruits certain polycomb proteins and DNA methyltransferases to participate in gene silencing of the tumor suppressor CEBPD." (PMID 39796650, 2024). "In addition, tumor cell proliferation was markedly inhibited only when both of KDM5C and YY1 were depleted in the KDM5C-proficient tumor cells ACHN and 769-P (H and EV1B)." (PMID 39433896, 2024). "Besides, YY1, SLC1A5, and Bcl-2 protein levels are significantly reduced, while Bax protein level is markedly enhanced in the tumor tissues of Silibinin-treated group." (PMID 38410123, 2024). "Moreover, we established xenograft tumor models by subcutaneously transplanting HCT116 cells with stable knockdown of USP7, YY1, or both into BALB/c nude mice." (PMID 38769122, 2024). "Five transcription factors (CREB1, CTCF, YY1, E2F1, MYBL2) were significantly elevated with tumor progression in HCC, indicating that these potential transcription factors may be responsible for the upregulation of H3–H4 histone chaperones in HCC." (PMID 38561384, 2024). "Considering these findings, we propose the following model: YY1 chromatin recruitment is at least partially dependent on the presence of KDM5C, and in tumor cells with high KDM5C expression, a small amount of YY1 can be recruited to chromatin even after KDM5C is knocked down." (PMID 39433896, 2024). "Thus, strategies to inhibit YY1 on CD8 T cells and tumor cells have been considered as new anti-tumor immune-therapeutic modalities." (PMID 39796650, 2024). "A correlation between YY1 and the immunosuppressive TME has been reported in several tumor types." (PMID 38339244, 2024). "On the other hand, YY1 seems to promote T cell exhaustion, a phenomenon that affects CD8+ T cells, in which persistent antigenic stimulation renders the cells hyporesponsive and incapable of eliminating tumor cells." (PMID 38339244, 2024). "Silibinin plays an anti-tumor role in GBM process, which may be achieved via inhibiting YY1/SLC1A5 pathway." (PMID 38410123, 2024). "Research findings suggest that YY1 exerts an influence over the expression of matrix metalloproteinases (MMPs), enzymes that degrade the extracellular matrix (ECM), facilitating tissue remodeling and creating pathways for tumor cell migration." (PMID 38893192, 2024). "Moreover, IHC staining shows a significant reduction in the number of Ki67, YY1, and SLC1A5-positive cells in the tumor tissues of the Silibinin-treated group." (PMID 38410123, 2024). "It is noteworthy that these analyses expanded on the pleiotropic role mediated by YY1 in the immunosuppressive TME by regulating various immune cellular compartments through the abundance of immunosuppressive cells and a reduction in anti-tumor immune cells." (PMID 38893192, 2024). "To determine whether OTUD3 promotes tumor progression by regulating YY1, we restored the expression of YY1 in endogenous OTUD3 depletion CRC cells or knocked down endogenous YY1 in OTUD3-overexpressing CRC cells." (PMID 38351178, 2024). "A peptide of the sequence of YY1’s OPB domain (IR4) was previously shown to inhibit YY1 binding to EZH2, reduce breast cancer cell viability, and efficiently inhibit the growth of a xenograft tumor." (PMID 37686614, 2023). "One such TF is called yin yang 1 (YY1) and plays important roles in tumor development." (PMID 37444616, 2023).
tumor (continued). "The IF results showed a significantly lower proportion of Ki‐67‐positive cells in the YY1 knockout xenograft tumours than the negative control group, suggesting that YY1 contributed to PCa cell proliferation in vivo." (PMID 37771187, 2023). "In addition, upregulation of RKIP in tumor cells also resulted in the upregulation of Fas via RKIP-mediated inhibition of NF-κB and downstream YY1." (PMID 37205308, 2023). "Additionally, KEGG analysis showed that compared to CENPA or YY1 alone, these genes co-regulated by CENPA+YY1 are specially enriched in some tumor-related signaling pathway such as cell cycle and cellular senescence." (PMID 37928273, 2023). "Treating tumor cells with DETA-NONOate resulted in the S-nitrosylation of YY1, leading to the inhibition of its DNA binding activity." (PMID 37444616, 2023). "Yin-Yang 1 (YY1) is a member of the GLI-Kruppel family of zinc finger proteins and plays a vital dual biological role in cancer as an oncogene or a tumor suppressor during tumorigenesis and tumor progression." (PMID 37081988, 2023). "Though previous studies have reported the presence of PARylation of YY1 under DNA damage in tumor cells, the sites of PARylation were not identified." (PMID 37582914, 2023). "Collectively, this study found that YY1 was regulated by ALKBH5 and YTHDF1-mediated m6A modification and served as an autophagy-dependent tumor driver to accelerate cancer progression through ATG4B transactivation, providing an exploitable therapeutic target for GC." (PMID 37724907, 2023). "In the case of patients with YY1 high in the tumor tissue, YY1 expression was also significantly higher in the adjacent normal tissue compared to that of patients with YY1 low at both mRNA and protein levels." (PMID 37444605, 2023). "Furthermore, NAP1L2 cooperated with YY1 to promote the transcription of MMP2 and MMP9, which promoted tumor metastasis." (PMID 36195720, 2023). "The stable knockdown of YY1 suppressed tumor growth and weight, as well as the Ki-67 expression (marker of proliferation) of xenografts in AGS cell-engineered athymic nude mice, suggesting that the inhibition of YY1 suppresses tumorigenesis in vivo." (PMID 37724907, 2023). "Our previous findings demonstrated that positive regulation of G6PD transcriptional activity by various transcription factors (including YY1, NeuroD1, PBX3, and p52-ZER6) enhances tumor cell proliferation by promoting tumor cell nucleotides and lipid biosynthesis." (PMID 38139067, 2023). "In addition, we detected a decrease in CENPA lactylation level and downstream genes protein level (such as YY1, CCND1 and NRP2), in 2-DG treated HCC tumor tissues." (PMID 37928273, 2023). "Inhibiting YY1 expression could have multiple effects on tumor cells, which can not only inhibit the proliferation, migration and EMT of tumor cells, but also enhance the effect of tumor immunotherapy." (PMID 37408047, 2023). "YY2 competes with YY1 to bind to SLC7A11 promoter and regulates it antagonistically, resulting in the opposite regulation on glutathione synthesis, ferroptosis, and tumor progression, indicating that YY2/YY1 homeostasis is crucial for maintaining redox homeostasis in tumors." (PMID 35246964, 2022). "Although the role of YY1 in cancer is controversial, with both oncogenic and tumor suppressor roles, YY1 acts as a strong negative regulator of periostin expression." (PMID 35954468, 2022). "The role of DDX3X in this kind of cancer has not been assessed, but it has been shown that in gastric, prostate and colon cancer cell lines, the interaction of DDX3X with YY1 is mediated by the circular DNA circ-CTNNB1, promoting tumor proliferation through the deregulation of the β-catenin axis." (PMID 35954483, 2022). "Furthermore, YY2 and YY1 bind competitively to the same DNA binding site in the SLC7A11 promoter and antagonistically regulate tumor cell ferroptosis, thus suggesting the molecular mechanism underlying their opposite regulation on tumorigenesis." (PMID 35246964, 2022).
tumor (continued). "Although the reduced number of HPA-deposited samples (12 Tumor and 3 Normal) does not allow to draw any statistically relevant conclusion, the images show a similar trend for both YY1 and RKIP protein levels." (PMID 35205667, 2022). "Yin-Yang 1 (YY1) is a transcription factor that may work either as an oncogene or a tumor suppressor, depending on the genotype and the phenotype of the tumor." (PMID 35205667, 2022). "Finally, these findings demonstrate that homeostasis between YY1 and YY2 is crucial for maintaining redox homeostasis in tumor cells." (PMID 35246964, 2022). "The BCPRS-related genes (YY1, POU5F1, NKX2-3, NR2F1, HEY1, and IFNA13) showed high heterogeneity in different cells; thus, the genes can independently predict cellular composition to reflect the microenvironment of tumor tissues." (PMID 34457116, 2021). "Furthermore, LINC00842 RNA levels as well as YY1, FASN, and acetylated PGC-1α protein levels were significantly and positively correlated with each other in PDAC tumor and normal tissues." (PMID 34158490, 2021). "Initially, the current study unveiled that YY1 was abundantly expressed in the LSCC cell lines and could potentiate LSCC cell proliferation and promote tumor growth." (PMID 34497757, 2021). "The transcription factors YY1 and CP2 act as tumor suppressors and promoters." (PMID 33315124, 2021). "In conclusion, YY1 could promote LSCC cell proliferation but inhibit apoptosis in vitro, thus promoting tumor growth in vivo." (PMID 34497757, 2021). "As YY1 upregulates TGF-β induced proliferation and migration in breast cancer cells, and O-GlcNAcylation stabilises TGF-β pathways, O-GlcNAcylation will have multiple effects on factors that promote tumour proliferation and immune suppression." (PMID 33375613, 2020). "Furthermore, YY1 affects the activity of enhancer of zeste homolog 2 (EZH2) in catalyzing histone H3 lysine 27 trimethylation (H3K27me3) and suppressing tumor suppressor miR-9 activity through DNA methylation." (PMID 32226547, 2020). "As a binding protein of RING1 and YY1, RYBP can exert a tumor suppressor effect and a good prognostic factor may depend on the role of RING1." (PMID 33634028, 2020). "TCONS_00012883 could promote the tumor growth and aggressiveness of cancer cells and activate the PI3K/AKT pathway through cooperating with DDX3 to facilitate the transactivation of YY1 and transcriptional alteration of MMP1." (PMID 33135346, 2020). "YY1 promotes G6PD transcription and enhances the PPP in tumor cells." (PMID 32226547, 2020). "In addition, tumor suppressive functions of MZF1-uPEP were mediated, at least in part, through interacting with YY1 protein in NB cells." (PMID 32042322, 2020). "Accordingly, YY1 knockdown disrupts the stability of HIF-1α and reduces its accumulation, resulting in the suppression of VEGF and tumor growth factor alpha (TGF-α), and subsequent inhibition of tumor angiogenesis and tumorigenesis." (PMID 32226547, 2020). "YY2 competes with YY1 in binding to the AES promoter, and as YY1 is abundantly expressed in tumour cells, it is enriched in the AES promoter region and could disturb YY2‐mediated AES transcription." (PMID 32969187, 2020). "This demonstrates the critical role of YY1 in lipid metabolism in tumor cells regardless of oxygen availability and tumorigenic stage, further supporting the role of YY1 as an important driver of tumorigenesis." (PMID 32226547, 2020). "YY1 regulates EMT, chemo sensitivity and tumor progression in cancer." (PMID 31703732, 2019).
tumor (continued). "YY1 is a GLI-kruppel family transcription factor that can activate or deactivate gene expression depending on binding partners and has a context dependent role as a tumor suppressor or a tumor growth promoter." (PMID 30764491, 2019). "Also, YY1 appear to positively regulate the oncogene HPV E6 and negatively regulate E-Cadherin and thereby promote tumor growth and metastasis." (PMID 31824839, 2019). "The mechanism by which YY1 brings out opposing outcome in tumor growth vs. suppression is not completely clear and some of the recent reports have provided significant insight into this." (PMID 31824839, 2019). "Expression of YY1 in CSCC tissues was not significantly correlated with tumor differentiation, but was significantly correlated with an advanced clinical stage of CSCC." (PMID 29470526, 2018). "Since Snail transcription is directly activated by YY1, we can hypothesize that RKIP eliminates tumor EMT characteristics by acting as a negative regulator of the NF-κB/YY1/Snail circuit." (PMID 30149591, 2018). "YY1 epigenetically silences miR-29, which is decreased in RMS patient samples and cell lines, and retroviral delivery of miR-29 to mice injected with Rh30 cells has been shown to slow tumor growth." (PMID 28883017, 2017). "Furthermore, we measured HDAC1 and YY1 levels in 50 pairs of HCC tissues and paired adjacent non-tumor tissues (ANLTs)." (PMID 28489564, 2017). "It is important to note that the association of YY1 and CSC transcription factors was based on analysis of expression patterns on whole tumor tissues and not on the CSC subsets." (PMID 27225481, 2016). "YY1 was predominantly expressed in the nuclei of tumor cells (left, case with negative YY1 expression; right, case with strong YY1 expression)." (PMID 24674326, 2014). "In 28 paired GAC cDNAs, 15 cases showed strong expression of YY1 in tumor tissue compared with adjacent non-tumorous tissue." (PMID 24674326, 2014). "Mechanistically, NO donors such as S-nitroso-N-acetylpenicillamine (SNAP) and DETA-NONOate can S-nitrosylate the transcriptional repressor YY1, impairing its ability to bind the Fas promoter silencer region, thereby enhancing Fas expression and sensitizing tumor cells to FasL-induced apoptosis." (PMID 41036604, 2025). "As a result of the interaction between YY1 and RYBP, the role of RYBP cannot be clearly explained, and some studies suggest that RYBP may support tumor progression by stabilizing PRC1 and repressing tumor suppressor genes, and its function seems dependent on the cellular context." (PMID 40867231, 2025). "YY1 cooperates with transcriptional coactivator PGC-1α and then enhances transcriptional activity of the ATP-binding cassette transporter 1 (ABCA1) gene, resulting in elevated ABCA1 expression levels, leading to insensitivity of colorectal cancer cells to isoliquiritigenin and tumor metastasis." (PMID 40867514, 2025). "Conversely, YY1 expression was negatively correlated with immune-reactive cells such as CD8 + T cells, follicular helper T cells, and memory B cells which are all critical for promoting anti-tumor immunity through cytokine secretion and enhancing T cell activation." (PMID 41327312, 2025). "For the first time, we demonstrated that SPANXB1 can upregulate MMP1 by modulating YY1 and histone H3R17me2 modifications, thus providing a novel insight into the role of SPANXB1 as a chromatin-binding protein and its potential as a therapeutic target for managing tumor metastasis." (PMID 40885703, 2025). "Moreover, YY1 induces vascular endothelial growth factor A (VEGFA) expression by directly binding to the promoter region of VEGF, thereby upregulating their transcription and promoting neovascularization to supply oxygen and nutrients to tumor cells." (PMID 38893192, 2024).
tumor (continued). "Furthermore, we discuss the potential of targeting YY1 and other strategies, such as nanocarrier delivery systems and engineered immune cells (CAR-T), to normalize tumor vascularization and re-establish an immune-permissive microenvironment to enhance the efficacy of cancer therapy." (PMID 38339244, 2024). "Herein we present the potential of targeting YY1, since it directly inhibits the expression of more than one inhibitory receptor on the CD8 T cells and thereby prevents the inactivation of CD8 T cells by the ligands bearing tumor cells, preventing cancer immune evasion." (PMID 39796650, 2024). "However, blocking PD-L1 via YY1 inhibition poses the need for a therapy that is specific and selective to tumor cells to ensure no adverse effects on healthy cells." (PMID 38539569, 2024). "To discover the prognostic value of YY1 and PEBP1 in pan-cancer, we analyzed differences in patient survival between high and low expression groups of the two genes, and found that the expression of both genes significantly (p < 0.05) correlates with survival in different tumor types." (PMID 37894300, 2023). "However, unlike YY1, which is upregulated in tumor tissues and is oncogenic, YY2 is downregulated in tumor tissues and is a tumor suppressor protein." (PMID 37444616, 2023). "Hence, in LC, YY1 might be considered a driver oncogene involved in the cellular transformation process, while RKIP might be considered a tumor-suppressor." (PMID 35205667, 2022). "Due to the limitation of experimental conditions, specific experimental and clinical studies could not be carried out to prove the possible function of YY1 in generalized tumor." (PMID 35791393, 2022). "As both NF-kB and YY1 concurrently upregulate the melatonergic pathway, this would be indicating a role for melatonergic pathway availability, especially the NAS/melatonin ratio, in determining neutrophil phenotype and effects within the tumor microenvironment." (PMID 36613754, 2022). "In addition, the ω-6 rich diet mediated the nuclear expression of NF-κB p65 that correlates with an increase in the expression and activation of YY1 that promotes the transcription of COX-2 and TGF-β, finally promoting a phenotype of greater tumor aggressiveness." (PMID 35682855, 2022). "However, we still cannot rule out that the high phosphorylation levels of S247 and S118 of YY1 are a byproduct of dysregulation of tumor cell signaling and have no functional significance in tumor cells." (PMID 35791393, 2022). "Although genetic changes may affect the level of mRNA expression, the findings of this study showed no significant variation in tumor copy number and nucleotide mutations of the six IMAAG genes (HEY1, IFNA13, NKX2-3, NR2F1, POU5F1, and YY1)." (PMID 34457116, 2021). "Although direct evidence is lacking, YY1 may also play an important role by affecting metabolic pathways in tumor cells." (PMID 33985581, 2021). "Importantly, YY1 can also facilitate HCC cell proliferation and tumor growth." (PMID 34863279, 2021). "In conclusion, our findings in the study confirmed that miR-34a overexpression could simultaneously suppress tumor growth and metastasis and play a vital role in tumorigenesis and progression of NSCLC via increasing PTEN and YY1 expression, but decreasing CDK6." (PMID 33796457, 2021). "Interestingly, the roles of YY2 in tumorigenesis are antagonistic to those of YY1, suggesting that YY2 might be a potential tumour suppressor." (PMID 32969187, 2020). "Thus, YY1 expression leads to the survival of tumor cells even under strong selective pressure, such as long-term estrogen deprivation by aromatase inhibitors, suggesting a role of YY1 in non-responder patients." (PMID 32226547, 2020).